RASGRP3 (RAS guanyl releasing protein 3)
Diseases named in the same sentence as RASGRP3 in open-access papers (continued):
Sharing a sentence is not in itself a finding about the gene and the disease.
Arthritis (1 paper, 2014). Inflammation of a joint. "We immunized RasGRP3 or RasGRP3-T133A transgenic mice with type II collagen of chicken on days 0 and 21, and found that the severity of arthritis in RasGRP3 transgenic mice was significantly regressed as compared with wild-type mice (day 52 after the primary immunization)." (PMID 25118589, 2014). "We demonstrate that RasGRP3, a dominant member of RasGRPs in macrophages, impairs TLR3/4/9-induced IL-6 production and relieves dextrane sulphate sodium-induced colitis and collagen-induced arthritis." (PMID 25118589, 2014).
atherosclerosis (1 paper, 2025). A disease characterized by the build-up of fatty material and calcium deposition in the arterial wall resulting in partial or complete occlusion of the arterial lumen. "On the other hand, while searching for a set of genes associated with the MAPK signaling pathway, we found a group of four DEG members of this pathway: PLA2G4A, IL1A, RASGRP3, and DDIT3, which are molecules related to inflammation, apoptosis, signal transduction, and atherosclerosis." (PMID 40332370, 2025).
breast ductal adenocarcinoma (1 paper, 2014). A breast carcinoma arising from the ducts. "However, to our best knowledge, we are the first to describe and quantitatively asses the expression of RasGRP3 and its active form on human breast ductal adenocarcinoma cells." (PMID 24779681, 2014).
breast tumor (1 paper, 2014). "Indeed, mutually complementary Q-PCR, Western blot and immunohistochemical analyses revealed that the expression of RasGRP3 and the active phosphoRasGRP3 are elevated in numerous human breast tumor samples as well as in multiple breast derived ductal adenocarcinoma cell lines." (PMID 24779681, 2014).
chronic graft versus host disease (1 paper, 2025). Chronic graft versus host disease (GVHD) is a complication that can occur after a stem cell or bone marrow transplant in which the newly transplanted donor cells attack the transplant recipient's body. "In another study that investigated lncRNA expression in chronic graft-versus-host disease, three lncRNAs (NONHSAT142151, NONHSAT040475 and FR118417) were found to strongly correlate with the expression of mRNAs related to the BCR signaling pathway (BTK, CD72, DAPP1, LILRB3, NFKBIE, RASGRP3)." (PMID 39940921, 2025).
colitis (1 paper, 2014). Inflammation of the colon. "To demonstrate the roles of RasGRP3-mediated regulation of macrophage responses in DSS-induced colitis, we transferred the RasGRP3 transgenic macrophages into irradiated wild-type mice and administered DSS." (PMID 25118589, 2014). "We found that colons derived from the RasGRP3 group demonstrated more mild colitis than those derived from wild-type group while colons derived from RasGRP3-T133A transgenic mice demonstrated the most severe colitis." (PMID 25118589, 2014). "We demonstrate that RasGRP3 transgenic overexpression inhibits TLR agonists-induced IL-6 production, decreases the inflammation severity of DSS-induced colitis and relieves the clinical scores of CIA." (PMID 25118589, 2014).
colon cancer (1 paper, 2014). "The G558R mutation of RasGRP3 detected in a colon cancer patient indicates that RasGRP3 may be associated with inflammation-related diseases, which may need validations in clinical samples derived from patients with SLE, RA or IBD." (PMID 25118589, 2014). "In human colon cancer samples, we detected a mutation of RasGRP3, G558R (G1672 mutated to A)." (PMID 25118589, 2014).
coronary atherosclerosis (1 paper, 2022). Atherosclerosis of the coronary vasculature. "Three significant DEGs—TOX, RasGRP3, and TSPAN13—were selected for IHC analysis based on their high fold changes and possible biological functions in the development of early coronary atherosclerosis to validate the bioinformatics analysis results." (PMID 36140731, 2022).
ductal adenocarcinoma (1 paper, 2014). "First, using Q-PCR and Western blot, we assessed the expression of the RasGRP3 protein and presumably its active form, phosphoRasGRP3, in human breast derived ductal adenocarcinoma (Tu) as well as in normal human breast tissue (Co) samples." (PMID 24779681, 2014). "Both in vitro and in vivo studies were carried out to define the exact functional role of RasGRP3 and the coupled intracellular signaling using RasGRP3 gene silencing in ductal adenocarcinoma derived MCF7 and T-47D cell lines." (PMID 24779681, 2014). "The RasGRP3 and phosphoRasGRP3 expressions were examined in human invasive ductal adenocarcinoma derived samples and cell lines (BT-474, JIMT-1, MCF7, SK-BR-3, MDA-MB-453, T-47D) both in mRNA (Q-PCR) and protein (Western blot; immunohistochemistry) levels." (PMID 24779681, 2014).
heart failure (1 paper, 2022). Inability of the heart to pump blood at an adequate rate to meet tissue metabolic requirements. "Additionally, the tissue RasGRP3 mRNA was remarkably elevated in mitral regurgitation patients with heart failure." (PMID 36140731, 2022).
prostate adenocarcinoma (1 paper, 2014). "For comparison, the relatively high expression of RasGRP3 in the PC-3 prostate adenocarcinoma derived cell line served as a positive control in both assays." (PMID 24779681, 2014).
ZIKV infection (1 paper, 2023). "Rasgrp3, also downregulated by ZIKV infection, activates the ERK/MAPK pathway through the Ras protein." (PMID 37301965, 2023).
tumor (14 papers, 2014 to 2026). "Levels of RasGRP3 at screening and after treatment also correlate with the best percent change in tumour volume from baseline." (PMID 36624219, 2023). "We have also presented that the relative level of RasGRP3 and phosphoRasGRP3 expressions in the tumor tissues was markedly higher compared to the normal tissues." (PMID 24779681, 2014). "In both cell lines, down-regulation of RasGRP3 resulted in a marked reduction in tumor growth as measured by weight of excised tumors in comparison of those induced by the shSCR-expressing cells." (PMID 24779681, 2014). "To assess furthermore the role of RasGRP3 in in vivo tumor formation, we employed the SCID mouse xenograft model in which tumors were induced by MCF7 and T-47D cells expressing either shRasGRP3 or shSCR." (PMID 24779681, 2014). "We found that the levels of RasGRP3 and phosphoRasGRP3, albeit exhibiting marked inter-individual variations, were significantly higher in the tumor samples compared to the controls." (PMID 24779681, 2014). "We then asked whether upregulation of RASGRP3 or FOXN3 contribute to the tumor suppressive role of FOXA1 in NPC cells." (PMID 32201519, 2020). "Moreover, several genes (such as BCAR3, GNAS, ISLR and RASGRP3) exhibited opposite patterns of AS events of a parent gene in tumor and normal tissues." (PMID 31695792, 2019). "Gene silencing of RasGRP3 reduced tumor formation in mouse xenografts as well." (PMID 24779681, 2014).
cancer (10 papers, 2011 to 2022). A tumor composed of atypical neoplastic, often pleomorphic cells that invade other tissues. "In recent years, RasGRP3 also has been reported to play a vital functional role in cancer formation and progression." (PMID 36140731, 2022). "RASGRP3 also has a physiological role in cancer, as does MN1, with both of these transcripts downregulated after both interventions." (PMID 31308645, 2019). "Three genes ASF1A, RASGRP3 and ZNF24 were not covered by any representative term and none of them is an NCG cancer gene." (PMID 34504716, 2021).
infection (2 papers, 2014 to 2015). The state of being infected such as from the introduction of a foreign agent such as serum, vaccine, antigenic substance or organism. "Our study suggests that RasGRP3 limits inflammatory response by activating Rap1 on low-intensity pathogen infection, setting a threshold for preventing excessive inflammatory response." (PMID 25118589, 2014). "We employed real-time PCR to detect 40 GAP and GEF genes and determined that the mRNA levels of SOS1, RasGRP3, Ect2, and Collybistin were increased in HepG2 cells after rAd-ASPP2 infection for 48 and 72 hours." (PMID 25980493, 2015). "RasGRP3, by enhancing Rap1-GTP, may set a threshold for preventing excessive inflammatory response to low levels of infection." (PMID 25118589, 2014). "The negative effects of RasGRP3 in regulating TLR responses on low levels of TLR ligands may represent innate ‘braking’ machinery for keeping macrophages from overactivation in case the infection is not fatally dangerous." (PMID 25118589, 2014).
adenocarcinoma (1 paper, 2009). A common cancer characterized by the presence of malignant glandular cells. "We found RasGRP3 −5.4-fold down-regulated in adenocarcinoma when compared with transgenic but otherwise unaltered cells and −6.9-fold down-regulated in a comparison with non-transgenic cells." (PMID 19812696, 2009).
RASGRP3 also shares sentences with these, for which no sentence is quoted: medulloblastoma (6 papers); colorectal cancer (2); Alzheimer disease (1); bacterial infection (1); brain tumor (1); CNS tumor (1); cold urticaria (1); endothelial dysfunction (1); epilepsy (1); gestational diabetes (1); infectious disease (1); Insulin resistance (1); leukemia (1); lung carcinoma (1); lupus nephritis (1); lymphoma (1); metastatic disease (1); metastatic prostate carcinoma (1); Mitral regurgitation (1); pancreatic cancer (1); prostate tumor (1).